CD14 (CD14 molecule)
Diseases named in the same sentence as CD14 in open-access papers (continued):
Sharing a sentence is not in itself a finding about the gene and the disease.
influenza (12 papers, 2011 to 2025). An acute viral infection of the respiratory tract, occurring in isolated cases, in epidemics, or in pandemics; it is caused by serologically different strains of viruses (influenzaviruses) designated A, B, and C, has a 3-day incubation period, and usually lasts for 3 to 10 days. "The phylum Defluviitaleaceae and the genus Defluviitaleaceae mediated 10.46% and 10.91% of their influenza protective effect by upregulating CD33+ HLA DR+ CD14- %CD33+ HLA DR+ cells." (PMID 39062949, 2024). "Alcaligenaceae and Dorea mediated their 21.10% and 18.55% protective effects against influenza by down-regulating the number of CD64 on CD14- CD16- cells, respectively." (PMID 39062949, 2024). "CD14 can be found either on the surface of macrophages or in soluble form in the serum, and CD14 plays a pro-inflammatory role leading to increased inflammation during influenza infection." (PMID 36386710, 2022). "Of them, many had relevance in influenza infection such as genes responsible for virus entry (Anxa1/2, Cd14), interferon signaling (Dusp10, Tnfsf13), or prostaglandin synthesis (Ptgs1/2)." (PMID 35629310, 2022). "Research also reported that blocking TLR4 or CD14 in mice can protect against influenza-induced acute lung injury." (PMID 36386710, 2022). "Among the most differentially expressed genes, myeloid cell nuclear differentiation antigen (MNDA) and cathepsin S (CTSS) were strongly upregulated in CD14+ monocytes after influenza vaccination." (PMID 34695164, 2021). "Together, the data show that influenza vaccination induces extensive transcriptomic changes in immune cells, including CD14+ monocytes." (PMID 34695164, 2021). "Because monocytes and macrophages have been suggested to play a key role in immune responses to influenza with age, we refocused our analyses on CD14+ peripheral blood monocytes." (PMID 35822051, 2021). "In addition, blocking of CD14 on human monocytes by specific antibody or use of CD14-deficient murine macrophages abolished influenza A virus-induced cytokine production suggesting CD14 is required for influenza-induced cytokine production during infection of mouse macrophages." (PMID 36386710, 2022). "Huoxiang Suling Shuanghua Decoction exerts an anti-influenza effect by affecting the expressions of mRNA and protein including TLR4, CD14, MyD88, NF-kB p65, HIF-1α, VEGF, IL17A, IL6, and inhibiting the accumulation of inflammation." (PMID 36386710, 2022). "Next, eight key targets were identified, including TLR4, CD14, MyD88, NF-κB p65, HIF1 α, VEGF, IL17A, and IL6, which were verified to be key targets for HSSD in the treatment of influenza." (PMID 36386710, 2022). "Single-cell RNA sequencing shows that transcriptional programs of both CD14+ monocytes and CD4+ T cells were considerably altered by the seasonal influenza vaccination." (PMID 34695164, 2021). "Furthermore, although we observed a reduced percentage of CD14+ve cells, this difference was not statistically significant and likely due to loss of CD14 expression following influenza-induced apoptosis rather than a specific influenza-mediated down-regulation of CD14, as previously suggested." (PMID 22238612, 2012). "Recent studies on adjuvanted influenza vaccination have demonstrated that increased chromatin accessibility in IRF-enriched regions, relative to AP-1-enriched regions, is critical for training CD14+ monocytes and enhancing antiviral immunity in myeloid cells." (PMID 40491958, 2025). "Notably, the down-regulation of CD64 on CD14- CD16- cells mediated 21.10% and 18.55% of the protective effect of Alcaligenaceae and Dorea against influenza, respectively." (PMID 39062949, 2024). "Multi-colour flow cytometry revealed that monocyte subsets expressed comparable levels of viral HA 8 h p.i., suggesting that influenza permissiveness is not restricted to specific monocyte populations, nor dependent on CD14, as has been reported for influenza-induced cytokine/chemokine release." (PMID 22238612, 2012).
influenza (continued). "Thus, the TLR4, CD14, MyD88, and NF-κB p65 in TLR4/NF-κB p65 signaling pathway, HIF1 α, VEGF, IL17A, and IL6 in HIF-1α/IL17 signaling pathway may be the targets responsible for the anti-inflammatory function of HSSD in treating influenza." (PMID 36386710, 2022). "In conclusion, our study suggested that TLR4, CD14, MyD88, NF-κB p65, HIF1 α, VEGF, IL17A, and IL6 in the TLR4/NF-κB p65 signaling pathway and HIF-1α/IL17 signaling pathway may be the key targets for the identified active compounds of HSSD to treat influenza by inhibiting inflammatory responses." (PMID 36386710, 2022).
osteoporosis (12 papers, 2016 to 2026). A condition of reduced bone mass, with decreased cortical thickness and a decrease in the number and size of the trabeculae of cancellous bone (but normal chemical composition), resulting in increased fracture incidence. "Increased levels of CD14+ monocytes or CD14+/CD16− monocytes are recognised as risk factors for osteoporosis." (PMID 41578166, 2026). "The weighted results of this method demonstrated a positive causal relationship between CD14+ monocyte count and osteoporosis (β = 0.096599, 95% CI: 1.06246, 1.141806, p = 1.46E−07)." (PMID 41578166, 2026). "Additionally, the CD14+/CD16− monocyte count was found to have a positive causal relationship with osteoporosis (β = 0.097927, 95% CI: 1.065098, 1.142008, p = 3.67E−08)." (PMID 41578166, 2026). "A prospective open-label trial compared the effects of denosumab and zoledronate on CD14+CD11b+ cells and CD14+CD11b+VNR+ cells over 48 weeks in postmenopausal women with osteoporosis." (PMID 39576015, 2024). "Overall, our study revealed that CD14+ monocytes contributed to the development of both osteoporosis and carotid atherosclerosis." (PMID 35937796, 2022). "miR-503-5p has also been found to be downregulated in CD14+ PBMCs from post-menopausal osteoporosis patients compared with healthy controls." (PMID 27005616, 2016). "The expression of miR-218-5p was decreased in CD14+ PBMCs from post-menopausal osteoporosis patients compared with healthy control." (PMID 27005616, 2016). "In contrast, the expression of miR-218-5p and miR-503-5p was decreased in CD14+ PBMCs from post-menopausal osteoporosis patients compared with healthy controls." (PMID 27005616, 2016). "In addition to cOCPs, CD14+ monocytes were diminished in the Dmab group compared with those in treatment-naive patients with osteoporosis." (PMID 39576015, 2024). "Since CD14 can initiate the signal transduction through TLR4 during the inflammatory response, abnormal TLR4 expression-associated osteoporosis may be partially mediated by the dysregulation of CD14." (PMID 38504994, 2024). "In addition, CD14+ monocytes, MOs, were diminished in the Dmab group compared with those in the osteoporosis group." (PMID 39576015, 2024). "Recent studies have revealed that the TNFSF members death receptor 3 (DR3) and one of its ligands, TNF-like protein 1A (TL1A) have a key role in secondary osteoporosis; enhancing CD14+ peripheral blood mononuclear cell (PBMC) osteoclast formation and bone resorption." (PMID 31299941, 2019). "In the present study, CD14+ monocytes isolated from human pre-menopausal females were utilized as a source of osteoclast precursors; as females are significantly more prone to developing osteoporosis and RA." (PMID 28062298, 2017). "In summary, since the high-level expression of RANK on CD14+ monocytes elevated osteoclastogenesis, these cells may play a crucial role in joint destruction and osteoporosis." (PMID 27822475, 2016). "We identified six variables that were predictive for OB differentiation: sex of the donor (p = 0.001), presence of osteoporosis (p = 0.004), intake of vitamin D supplements (p = 0.003), fraction of CD146+ cells (p = 0.004), fraction of ALP+ cells (p = 0.005), and CD14+ cells (p = 0.089)." (PMID 33941262, 2021).
osteosarcoma (12 papers, 2015 to 2024). A usually aggressive malignant bone-forming mesenchymal neoplasm, predominantly affecting adolescents and young adults. "A high number of CD14+/HLA-DRα+ macrophages was also associated with a better OS, vascularity and a better response to chemotherapy treatment in osteosarcoma; however, the M2 phenotype of CD14+/CD163+ macrophages was not related to OS." (PMID 37958467, 2023). "proved that TAMs defined as CD14-expressed cells were associated with metastasis suppression and better overall survival in high-grade osteosarcoma patients." (PMID 33363016, 2020). "CD14+ macrophage M2 is associated with reduced metastasis and better survival in osteosarcoma." (PMID 34335756, 2021). "TAMs expressing CD14 or CD163 are associated with improved overall survival and metastasis-free survival in multiple osteosarcoma cohorts." (PMID 39359731, 2024). "Looking at tumor tissue, they found massive infiltration of CD14+ monocytes in osteosarcoma compared to Ewing sarcoma but found limited T cell infiltration." (PMID 38542199, 2024). "On the other hand, in osteosarcoma, CD14+HLA-DR+ M1 macrophages and CD14+CD163+ M2 macrophages were observed." (PMID 37958467, 2023). "The highest expression was in reticulocytes, hepatoblastoma, osteosarcoma, bone marrow, and CD14+ monocytes (the latter were in the top 15 expressors for the antisense too)." (PMID 35884374, 2022). "hM-CSF and 50% osteosarcoma-conditioned medium were used to treat CD14+ PBMCs to form TAM-like macrophages." (PMID 34686652, 2021). "We describe the immune status using flow cytometry of peripheral blood in patients with osteosarcoma and Ewing sarcoma and demonstrate excessive CD14 in tumor tissues." (PMID 26286851, 2015). "Interestingly, CD11b+CD14+MHCII− monocytes isolated from the peripheral blood of a dog with osteosarcoma were able to inhibit T cell proliferation, showing immunosuppressive activity." (PMID 36009726, 2022). "In addition, four macrophage-related prognostic genes (IL10, VAV1, CD14, and CCL2) had been identified, and the macrophage-related risk model had been validated to be reliable for evaluating prognosis in osteosarcoma." (PMID 34335756, 2021). "A comprehensive study described that CD14+/CD68+ TAMs represent the main infiltrating immune cell types in bone sarcomas, including osteosarcoma." (PMID 33363016, 2020). "Further characterization of four DC subclusters based on CD14/CD163, cDC1, cDC2, and CCR7 marker positivity demonstrates a higher number of cDC2 found in the TME of metastatic lung lesions than in primary and recurrent osteosarcoma." (PMID 39359731, 2024). "Our results indicated that the relative mean fluorescence (RMFI) of CD163, CD206, and PD1 was increased in osteosarcoma tissues compared with para-osteosarcoma tissues, while, the expression of CD14 and CD16 did not change." (PMID 32908942, 2020). "Because most osteosarcoma patients have anemia, which can induce high levels of EPO and TAMs in osteosarcomas express EPOR, verify that EPO plays a role in the protumor function of TAMs, we cultured primary TAMs collected from patients with osteosarcoma lung metastases using CD14 microbeads." (PMID 32908942, 2020).
fibrosis (11 papers, 2010 to 2023). the formation of excess fibrous connective tissue in an organ or tissue in a reparative or reactive process. "The association between F3/F4 fibrosis and the liver fibrosis score (LFS) algorithm was improved by inclusion of the CD14+ or CD16+ leukocyte EV frequency, each of which also improved the risk prediction of F3/F4 fibrosis in NAFLD." (PMID 34202136, 2021). "Some of the most significantly activated canonical pathways included hepatic fibrosis/hepatic stellate cell activation (CD14, COL1A1, FGFR2, IGFBP3, MMP2, and TGFBR1), and p38 MAPK signaling pathways (CREB1, PLA2G2A, TGFBR1)." (PMID 20540791, 2010). "In this work, we show that the transcription of Tlr4 and Cd14 is upregulated in the liver of Sj-infected mice, and that suppression of TLR4 signaling by TAK242 decreases the extent of hepatic fibrosis induced by Sj infection." (PMID 29321784, 2017).
Granuloma (11 papers, 2013 to 2025). A compact, organized collection of mature mononuclear phagocytes, which may be but is not necessarily accompanied by accessory features such as necrosis. "The downmodulation of CD14 appears to be supportive for RuV infection of MΦs and could potentially be involved in RuV maintenance, as it was shown in association with M2 MΦs in granulomas of PID patients." (PMID 35203475, 2022). "Mediation of local inflammation.Percentage of CD14+CD16+ Mo correlates with disease activity.Boost the formation of granulomas in CD." (PMID 31178867, 2019). "The granulomas had a higher percentage of dendritic cells stained for phagocytic markers CD11c, CD14, and CD16/CD32 than they had macrophage." (PMID 24198843, 2013). "Finally, we saw upregulation of mTOR in CD14 monocytes; induced overactivity of this pathway was sufficient to generate spontaneous granulomas in a recent mouse model." (PMID 33363531, 2020). "However, Kv induced granulomas have histologically been detected at 6–24 hrs and resulted in a CD4+ and CD14+ monocyte assembly at 48 hrs after intradermal inoculation." (PMID 28114394, 2017). "We identified calprotectin+ myeloperoxidase+ CD11b+ neutrophils, CD14+/CD68+ monocytes/macrophages, CD3+ T cells, CD3-CD7+ NK cells, CD20+ B cells, CD3+ TCRγδ+ T cells, CD117+ ILC, cytokeratin+ epithelial cells and undefined cells with heterogeneous distribution across all 28 granulomas." (PMID 40749077, 2025). "No HEVs were detected within or around CD14+/CD15+ granulomas." (PMID 27148274, 2016).
lymphopenia (11 papers, 2014 to 2024). Reduction in the number of lymphocytes. "As observed in previous studies, our cohort of patients exhibit a profound lymphopenia and alterations of the myeloid compartment, with an increase of circulating “dysfunctional” CD14+CD163+ and CD14+HLA-DRlow monocytes as compared to controls." (PMID 34322128, 2021). "Functional enrichment analysis also highlighted a marked shift in cellular population within the circulation with a significant enrichment for transcriptional profiles associated with CD14 + monocytes and CD33 + myeloid cells, underscoring the lymphopenia observed in COVID19 + ICU patients." (PMID 33306162, 2020). "Additionally, increased IFN-γ promotes myeloid cell activation which is observed in the augmented frequency of inflammatory CD14+, CD16+, CCR5+ monocytes in the PASC group compared to healthy donors, supporting lymphopenia and virus persistence in these patients." (PMID 34262570, 2021).
Parkinson disease (11 papers, 2011 to 2025). A progressive degenerative disorder of the central nervous system characterized by loss of dopamine producing neurons in the substantia nigra and the presence of Lewy bodies in the substantia nigra and locus coeruleus. "In the current study, the scioDiscover proteomic screening platform detected elevated CD14 levels in plasma samples from patients with Parkinson’s disease compared to controls." (PMID 39767701, 2024). "In fact, elevated levels of a soluble form of CD14 were recently seen in CSF from AD and Parkinson's disease (PD) patients compared with healthy controls." (PMID 22114747, 2011). "Recent studies have shown that CD38 on Plasma Blast-Plasma cells was associated with a lower risk of Parkinson’s disease, CX3CR1 on CD14- CD16- monocytes was associated with a lower risk of developing cerebral aneurysms and was associated with a higher risk of chronic pancreatitis." (PMID 40328660, 2025). "However, a previous study detected upregulated CD14 levels in post mortem brain tissues of a murine model of Parkinson’s disease." (PMID 39767701, 2024). "More importantly, expression levels for TLR2, TLR5, and CD14 are increased in Parkinson’s disease." (PMID 25586882, 2015). "To further elucidate the involvement of peripheral immune cells, we studied epigenome-wide DNA methylation in isolated populations of CD14+ monocytes, CD19+ B cells, CD4+ T cells, and CD8+ T cells from Parkinson’s disease patients and healthy control participants." (PMID 37903812, 2023).
ulcerative colitis (11 papers, 2012 to 2025). An inflammatory bowel disease involving the mucosal surface of the large intestine and rectum. "Recent studies investigating sCD14 levels in children recruited from the general population or ulcerative colitis patients found an association between sCD14 serum levels and CD14 SNP genotypes." (PMID 36238273, 2022). "Previous studies showed that the polymorphism in the promoter of the human CD14 gene was associated with CD and ulcerative colitis (UC), either alone or through interaction with polymorphisms in the CARD15/NOD2 gene." (PMID 22605977, 2012). "Lipopolysaccharide-binding proteins, Toll-like receptor 4, and bacterial permeability-increasing proteins have been detected in the serum of patients with ulcerative colitis, and these complexes are recognized by CD14." (PMID 39995691, 2025). "The median fluorescence intensity of CD44 on CD44+CD14+ lymphocytes was nearly 2-fold higher in ulcerative colitis patients treated with biological therapy in comparison to the NBT group." (PMID 36010364, 2022). "In this study, we detected higher CD44 expression in minor CD44+CD14+ lymphocyte subpopulation in biologically treated ulcerative colitis compared to NBT." (PMID 36010364, 2022). "Median fluorescence intensity (MFI) of CD44 on CD44+CD14+ lymphocytes was higher in ulcerative colitis patients treated with biological therapy compared to NBT." (PMID 36010364, 2022). "Another study identified Acinetobacter in the CD14+CD11c + CD163low subset macrophages in the lamina propia of ulcerative colitis patients, which indicates these microbes were able to bypass the epithelial barrier." (PMID 35685287, 2022). "Notably, the expression pattern of CD86 and CD14 in mucosal cells as observed in the organ culture model resembles that in intestinal inflammation in vivo (ulcerative colitis)." (PMID 24841635, 2014). "This fact is not exclusive to RA, and we previously found an increased percentage of CD14+PLT+ and a lower expression of mCD162 on monocytes in other chronic inflammatory diseases, such as ulcerative colitis and SLE." (PMID 35628558, 2022). "In four of the five ulcerative colitis patients, biopsies taken after 7d dosing demonstrated V565 in the lamina propria with co-immunostaining on CD3+ T-lymphocytes and CD14+ macrophages." (PMID 31575982, 2019). "Median values (with interquartile ranges) for percentages of non-classical CD14+CD16++ monocytes, which were decreased in the Crohn’s non-bio group, in each group were: ulcerative colitis bio, 8.545 (7.34–13.39); ulcerative colitis non-bio, 8.16 (5.39–8.9); and control 7.54 (6.15–9.27)." (PMID 36010364, 2022).